CD226 (CD226 molecule)
Diseases named in the same sentence as CD226 in open-access papers (continued):
Sharing a sentence is not in itself a finding about the gene and the disease.
colorectal cancer (9 papers, 2017 to 2025). A primary or metastatic malignant neoplasm that affects the colon or rectum. "CD226 encodes a glycoprotein expressed on the surface of blood cells and is related to colorectal cancer, which could be a potential biomarker of obesity." (PMID 37205363, 2023). "In this study, we aimed to assess the prognostic value of CD226 in tumor-infiltrating lymphocytes (TILs) derived from colorectal cancer (CRC) liver metastases treated with chemotherapy and radical surgery." (PMID 36717657, 2023). "Tumor-intrinsic expression of TIGIT has been reported in patients with colorectal cancer, and was shown to promote tumor progression by competing with CD226 in binding to CD155." (PMID 36163179, 2022). "Downregulation of CD226 on tumor‐infiltrating CTLs has been reported in several solid malignancies, such as non‐small cell lung carcinoma (NSCLC) squamous cell carcinoma, and colorectal cancer." (PMID 39777847, 2025).
sarcoma (9 papers, 2017 to 2022). A usually aggressive malignant neoplasm of the soft tissue or bone. "In line with this, MCA-derived sarcomas and DMBA-derived papillomas originated in DNAM1-deficient (Cd226−/−) mice were shown to express higher levels of the DNAM1-activating ligand CD155." (PMID 33546248, 2021). "It was reported that the KLRK1 axis is becoming an emerging target in cancer immunotherapy, and the overexpression of CD226 or KLRK1 on NK cells resulted in efficient anti-sarcoma activity." (PMID 33549054, 2021).
systemic sclerosis (9 papers, 2012 to 2025). A chronic disorder, possibly autoimmune, marked by excessive production of collagen which results in hardening and thickening of body tissues. "Genome-wide association analyses in European ancestry cohorts have identified the CD226 rs763361 T allele as a genetic risk locus for systemic sclerosis, demonstrating particularly strong associations with severe clinical phenotypes including diffuse cutaneous involvement." (PMID 40723878, 2025). "Association of CD226 haplotype block in the Fib+ subset of systemic sclerosis patients." (PMID 22531499, 2012). "In systemic sclerosis patients’ skin tissue, CD226 overexpression exacerbates fibrotic progression by enhancing T cell infiltration and prompting the secretion of pro-inflammatory cytokines including TNF-α and IL-6." (PMID 40723878, 2025). "In systemic sclerosis patients, elevated CD226 expression in CD8+ T cells promotes profibrotic IL-13 production and endothelial damage." (PMID 40723878, 2025). "Subsequently, CD226 was also found to promote inflammation, as demonstrated on mice models of dermal fibrosis in systemic sclerosis and acute graft-versus-host disease." (PMID 36421930, 2022). "Later, CD226 was also found to promote inflammation-driven dermal fibrosis in a mouse model of systemic sclerosis 22 and contribute to development of acute graft-versus-host disease (GVHD) in mice." (PMID 32104514, 2020).
experimental autoimmune encephalomyelitis (6 papers, 2015 to 2022). An autoimmune demyelinating disease of the central nervous system that is produced experimentally in animals by the injection of homogenized brain or spinal cord in Freund's adjuvant. "TIGIT knock-out mice are more susceptible to the development of spontaneous experimental autoimmune encephalomyelitis (EAE), suggesting an important role for the CD226/TIGIT pathway in autoimmune responses." (PMID 34298735, 2021). "Recently, we reported treatment targeting CD226 can ameliorate experimental autoimmune encephalomyelitis (EAE) by promoting IL‐10 expression via regulation of CD4+ T cell differentiation." (PMID 29299389, 2017). "Treatment targeting CD226 can ameliorate experimental autoimmune encephalomyelitis (EAE), the widely accepted model of MS." (PMID 26942885, 2016). "In this study, we showed that Cd226−/− mice were resistant to myelin oligodendrocyte glycoprotein peptide 35-55 (MOG35−55)-induced experimental autoimmune encephalomyelitis (EAE) with highly expressed IL-10+CD4+ T cells and downregulated IL-17A+CD4+ T cells when compared with wild-type (WT) mice." (PMID 32983109, 2020).
gastric cancer (6 papers, 2013 to 2025). A primary or metastatic malignant neoplasm involving the stomach. "In gastric cancer, high CD226+CD8+ T cell infiltration predicts better survival and response to adjuvant chemotherapy." (PMID 40723878, 2025). "Nonetheless, two recently published studies showed a favorable prognosis for CD226 on immune cells of gastric cancer." (PMID 41181119, 2025). "Herein, we showed a crucial regulatory role of CD226 in CD8+T cell-mediated anti-tumor response in TME of human gastric cancer (GC)." (PMID 37056782, 2023).
glioblastoma (6 papers, 2013 to 2025). The most malignant astrocytic tumor (WHO grade IV). "In glioblastoma, CD155 has also been established as an immunomodulatory receptor, able to both activate NK cells through interactions with CD226 (DNAM-1) and CD96 and inhibit them through interaction with TIGIT." (PMID 35803912, 2022). "In contrast, CD155, the other ligand of CD226 was not expressed in the adult central nervous system (CNS), but was expressed in glioblastoma." (PMID 29299389, 2017). "This may not be the case for all cancers, as TIGIT and CD226 were co-expressed in glioblastoma multiforme and in melanoma." (PMID 37596248, 2023).
HIV-1 infection (6 papers, 2012 to 2025). The type species of lentivirus and the etiologic agent of acquired immunodeficiency syndrome (AIDS). "CD226+NK cells in chronic infection over 2 years were fewer than that in the first, third, twelfth month after HIV-1 infection (all P < 0.05)." (PMID 33717085, 2021). "TIGIT and CD226 coexpression on NK cells was downregulated until in chronic HIV-1 infection over 2 years, though it is insignificant (P = 0.053)." (PMID 33717085, 2021). "Increasing TIGIT-mediated inhibition of CD8 T-cells and parallel downregulation of CD226 has been reported in HIV-1 infection despite early initiation of antiretroviral therapy (ART)." (PMID 34712231, 2021). "In this study, CD96−CD226+ cells in total NK cells including TIGIT+NK and TIGIT−NK cells significantly diminished, while CD96+CD226− cells expanded at all the acute and chronic phases of HIV-1 infection, which indicated that the expression of these two NK subset cells were oppositely affected." (PMID 33717085, 2021). "In this study, we demonstrated the dynamics of TIGIT, CD96 and CD226 expression and functions in NK cells in the first, third and twelfth month after HIV-1 infection in our Beijing PRIMO clinical cohort and chronic HIV-1 individuals with over 2 years of infection." (PMID 33717085, 2021). "Furthermore, despite the close relationship and similar characteristics of CD96 and CD226, they are differentially affected by HIV-1 infection." (PMID 23272144, 2012). "Contrary to the upregulated TIGIT expression on NK cells, CD96, which shares the ligand of CD155 with CD226 and TIGIT, was upregulated on NK cells in both acute and chronic HIV-1 infection." (PMID 33717085, 2021). "Although CD155, as the ligand of TIGIT, CD226 and CD96, is rarely expressed on CD4 T cells, it was upregulated in acute and chronic HIV-1 infection." (PMID 33717085, 2021). "CD226 is a co-stimulatory molecule that is involved in the proliferation and differentiation of T-cells and important for effector functions of CD8 T-cells and NK cells in HIV-1 infection." (PMID 34712231, 2021). "However, the expression of CD226 was not downregulated until in more than 2 years of chronic HIV-1 infection." (PMID 33717085, 2021). "CD226 was not modulated by HIV-1, whereas CD155 and NTB-A were down-regulated upon HIV-1 infection, also dependent on the concerted action of Vpu and Nef." (PMID 40911682, 2025).
lymphoma (6 papers, 2016 to 2025). A malignant (clonal) proliferation of B- lymphocytes or T- lymphocytes which involves the lymph nodes, bone marrow and/or extranodal sites. "IRF4 has been known to regulate the expression of costimulatory molecules (CD80/CD86) and MHC-class-II-dependent antigen presentation in multiple immune cell types, including dendritic cells, CD226+ macrophages, and lymphoma B cells." (PMID 40585371, 2025). "We validated this correlation by demonstrating that the latency III characteristic EBV NF-κB activator, latent membrane protein 1 (LMP1), was sufficient for CD226 upregulation and that CD226 was more highly expressed in lymphomas with increased NF-κB activity." (PMID 29202043, 2017). "In this article, we characterize the mechanism by which EBV induces this protein and its expression on lymphoma tissue and cell lines and characterize EBV-infected cell lines in which CD226 has been knocked out." (PMID 29202043, 2017). "CD226 is expressed on different hematopoietic cells including CD8+ T cells and contributes to their activation, expansion and differentiation but its deficiency in mice did not induce lymphomas, suggesting that this gene may not be a tumor suppressor gene." (PMID 27690235, 2016).
metastatic melanoma (6 papers, 2016 to 2023). A melanoma that has spread from its primary site to another anatomic site. "CD8+ TILs exhibited downregulation of the costimulatory molecule CD226, which competes with TIGIT for the same ligand, supporting a TIGIT/CD226 imbalance in metastatic melanoma." (PMID 29996914, 2018). "In a separate cohort of patients with metastatic melanoma, we confirm that that the peak eSNP for CD226 is a determinant of CD226/DNAM1 protein expression on NK cells (p = 0.03)." (PMID 35835762, 2022). "In patients with metastatic melanoma, CD8+ TILs upregulate TIGIT and downregulate CD226, leading to an imbalance of TIGIT/CD226 expression." (PMID 31379886, 2019).
non-small cell lung carcinoma (6 papers, 2020 to 2025). A group of at least three distinct histological types of lung cancer, including non-small cell squamous cell carcinoma, adenocarcinoma, and large cell carcinoma. "CD36, CD41, CD61, and CD226 upregulated on LDNs associated with non-small-cell lung cancer (NSCLC) and CD10, CD16, and CD45high present a mature phenotype with T cell-suppressive role in blood cancer." (PMID 41009604, 2025). "CD226 expression is also associated with clinical benefits in patients with non-small cell lung carcinoma treated with anti-PD-L1." (PMID 36717657, 2023). "CD226 expression associated with clinical benefit in patients with non-small cell lung carcinoma (NSCLC) treated with anti-PD-L1 antibody atezolizumab." (PMID 35263569, 2022). "We next asked whether CD226 expression was also a determinant for clinical responses to atezolizumab, an anti-PD-L1 mAb, in patients with non-small cell lung carcinoma (NSCLC)." (PMID 35263569, 2022).
Obesity (6 papers, 2016 to 2025). Accumulation of substantial excess body fat. "Given that CD226 deficiency improved obesity and its related systemic inflammation, we investigated the inflammatory phenotype of the accumulated ATMs." (PMID 34823548, 2021). "In the present study, we utilized CD226 knockout (KO) mice to observe the roles of CD226 deficiency in the obesity and its related systemic inflammation induced by a high-fat diet (HFD)." (PMID 34823548, 2021). "We found that deficiency of CD226 alleviated obesity and inflammatory state via inhibition of the ATM accumulation and the proinflammatory phenotype of macrophages." (PMID 34823548, 2021). "Combined with these literatures, the elevated PPAR-γ activation caused by CD226 deficiency may also partially contribute to the ameliorated obesity-related fatty liver through suppression of chemokines." (PMID 34823548, 2021). "In conclusion, we proposed that CD226 deficiency could alleviate the severity of HFD-induced obesity via inhibition of the accumulation and M1 polarization of ATMs and secretion of proinflammatory cytokines." (PMID 34823548, 2021). "This indicates potential roles of CD226 in obesity-associated metabolic diseases." (PMID 34823548, 2021). "It has been found that the knockdown of CD226‐stimulating molecules to inhibit macrophage M1 polarization reduces systemic inflammation, thereby reducing obesity." (PMID 41292674, 2025). "In the present study, we clarified the potential roles of CD226 in HFD-induced obesity and its related systemic inflammation." (PMID 34823548, 2021). "Using a high-fat diet (HFD)–induced mouse obesity model, we found that the costimulatory molecule CD226 was highly expressed on ATMs and knockout (KO) of CD226 alleviated obesity caused by HFD." (PMID 34823548, 2021). "Combined with the highly expressed CD226 in the obesity patients, our findings support the use of anti-CD226 for the treatment of obesity and its related metabolic disorders." (PMID 34823548, 2021). "Although CD226 KO mice on a HFD developed obesity, they were partially protected from the development of glucose intolerance." (PMID 26910838, 2016). "Here, we observed that CD226 was highly expressed in the obesity population and ATMs." (PMID 34823548, 2021). "To determine whether CD226 is involved in the occurrence of HFD-induced obesity, we examined the metabolic phenotype of CD226KO mice." (PMID 34823548, 2021). "However, exact roles of CD226 on ATMs during obesity and adipose tissue inflammation remain unclear." (PMID 34823548, 2021).
acute graft versus host disease (5 papers, 2015 to 2024). A syndrome of immunologically mediated tissue damage that may occur following an allogeneic transplant, usually affecting the skin, liver, and GI tract. "DNAM-1 (CD226) is an activating immunoreceptor expressed on T cells and NK cells and involved in the pathogenesis of acute graft-versus-host disease (aGVHD) after allogeneic hematopoietic stem cell transplantation (allo-HSCT)." (PMID 32040515, 2020). "We found weak genetic associations between polymorphisms in the CD226, CD244, FCGR3A, KLRD1, NCR3, and PVRIG genes, and the risks for relapse, acute GVHD, and chronic GVHD in the HSCT discovery cohort but not in the replication cohort." (PMID 39506082, 2024).
allergic disease (4 papers, 2022 to 2025). An immune response that occurs following re-exposure to an innocuous antigen, and that requires the presence of existing antibodies against that antigen. "Despite the critical roles of this checkpoint receptor in T cell immunoregulation, the effects of CD226 against allergic diseases, such as asthma, and the underlying mechanisms remain largely unknown." (PMID 39349422, 2024). "It is unknown if CD226 modulates other dominant cells, including Th2 cells and type 2 innate lymphoid cells, in airway allergic diseases." (PMID 35846105, 2022). "Our findings were observed in global Cd226 KO mice and CD4+ T cell-specific Cd226 KO mice; however, we did not rule out the possibility that CD226 on other immune cells may play a critical role in the development of allergic reactions." (PMID 35846105, 2022). "In this study, the impact of elevated levels of TIGIT cannot be ruled out, the role of TIGIT in T cell apoptosis and allergic diseases, and whether TIGIT interacts with CD226 and affects CD226 function, should be explored in future studies." (PMID 39349422, 2024).
autoimmune thyroid disease (4 papers, 2011 to 2024). Inflammatory disease of the thyroid gland due to autoimmune responses leading to lymphocytic infiltration of the gland. "Diseases related to CD226 mutations include a variety of autoimmune endocrine disorders, such as autoimmune thyroiditis (AITD)." (PMID 36123715, 2022). "This study aimed to assess the prevalence of selected single-nucleotide polymorphisms (SNPs) of Il7R, CD226, CAPSL, and CLEC16A genes in children with autoimmune thyroid diseases." (PMID 38612837, 2024). "The aim of this study was to assess the prevalence of selected single-nucleotide polymorphisms (SNPs) of Il7R, CD226, CAPSL, and CLEC16A genes in children and adolescents with autoimmune thyroid diseases, and in the control group." (PMID 38612837, 2024).
osteosarcoma (4 papers, 2020 to 2024). A usually aggressive malignant bone-forming mesenchymal neoplasm, predominantly affecting adolescents and young adults. "The expression of PVRL2 and PVR by osteosarcoma cell lines add more complexity to the TIGIT/CD226 signaling network." (PMID 38791381, 2024). "Osteosarcomas have been previously shown to express CD155 (Poliovirus Receptor, PVR), which is one of the ligands for DNAX accessory molecule-1 (DNAM-1 or CD226), an activating receptor expressed on NK cells, monocytes and a subset of T cells." (PMID 32082316, 2020).
preeclampsia (4 papers, 2021 to 2025). Preeclampsia is a hypertensive disorder of pregnancy that is characterized by new-onset hypertension with proteinuria presenting after 20 weeks of gestation, and depending on mild or severe forms may initially present with severe headache, visual disturbances, and hyperreflexia. "Dysregulation of immune checkpoint pathways, like the TIGIT/CD226 axis, has been implicated in complications such as recurrent implantation failure and preeclampsia, suggesting a role for checkpoint modulation in therapeutic strategies." (PMID 39796279, 2025). "The CD226/TIGIT MFI ratio on the surface of the NK cell subpopulations showed a significant decrease in all the investigated NK subpopulations in EO preeclampsia compared to the healthy controls." (PMID 39125946, 2024). "Another novel observation is a decreased CD8− NKdim CD226 expression tendency compared to the CD8− counterpart in the EO preeclampsia group." (PMID 39125946, 2024). "Measuring the CD226 expression, significantly decreased surface receptor expression level was detected by the NK-, NKdim-, and NKbright cell subpopulations in women with EO preeclampsia compared to the healthy pregnant control group." (PMID 34829838, 2021). "Examination of the NKT cell subpopulation significantly elevated frequencies were measured in TIGIT+/CD226− and TIGIT−/CD226− subsets in EO preeclamptic cohort compared to healthy cohort; however, the frequency of the TIGIT−/CD226+ subpopulation was significantly decreased in EO preeclampsia." (PMID 34829838, 2021). "This pattern is quite similar in the case of the investigated T cells; therefore, the presence of the CD226 activatory receptor could play a role in disturbing immune responses related to EO preeclampsia." (PMID 34829838, 2021). "Since CD226 is constitutively expressed on the surface of the majority of T lymphocytes and NK cells, the reduction in the surface presence could result from the Th1 predominance during EO preeclampsia." (PMID 34829838, 2021). "A recent study by our group examined the TIGIT, CD226, CD112, and CD155 immune checkpoint molecules in the peripheral blood mononuclear cells of women diagnosed with early-onset preeclampsia." (PMID 39125946, 2024). "Similar to TIGIT, the expression level of the activating immune checkpoint receptor CD226 was also significantly lower by CD3+ T-, CD4+ T, CD8+ T, and NKT-like cells in women diagnosed with EO preeclampsia compared to the healthy pregnant cohort." (PMID 34829838, 2021). "We assume that immune checkpoint molecules, including TIGIT/CD226/CD112/CD155, have an essential role in the regulation of the Th1 predominance, which is initiated by intrinsic factors released by the poorly developed placenta during EO preeclampsia." (PMID 34829838, 2021). "Significantly decreased CD226 expression and increased CD112 and CD155 surface expression were detected in almost all investigated T-cell, NK cell, and monocyte subpopulations in women diagnosed with preeclampsia compared to the healthy group." (PMID 34829838, 2021). "Moreover, there is no available information about the TIGIT, CD226, CD112, or CD155 immune checkpoint molecules in any context of preeclampsia." (PMID 34829838, 2021).